RAC1P3 (Rac family small GTPase 1 pseudogene 3)
Synonyms: Psi3Rac1
Gene: Processed pseudogene on chromosome 13 (41,287,741 to 41,288,320, reverse strand). Ensembl gene ENSG00000231404.
Diseases named in the same sentence as RAC1P3 in open-access papers:
RAC1P3 is named in the same sentence as 2 diseases in open-access papers, as found by Europe PMC text mining. Sharing a sentence is not in itself a finding about the gene and the disease. The quoted sentences say what the papers report.
cancer (1 paper, 2023). A tumor composed of atypical neoplastic, often pleomorphic cells that invade other tissues. "Some are known to be tumor suppressor genes (OPCML-IT2), to be related to resistance to cancer therapies (RAC1P3), or to be involved in several cancer processes such as genome stability (XRCC6P2), tumor growth and metastasis (MIR602) and regulation of gene transcription (NME2P2)." (PMID 36647008, 2023).
RAC1P3 also shares sentences with these, for which no sentence is quoted: tumor (1 paper).